IL6 (interleukin 6)
Diseases named in the same sentence as IL6 in open-access papers (continued):
Sharing a sentence is not in itself a finding about the gene and the disease.
bacterial infection (continued). "The potency of the tested flavonolignans to modulate the immune response was determined on LPS-induced macrophages by monitoring cytokine (TNF-α and IL-6) release as the first reaction, by which a healthy cell responds to the bacterial infection." (PMID 32466263, 2020). "The cytokine IL-6 is largely described for its protective role in immune responses against bacterial infections." (PMID 33322581, 2020). "Verifying the data obtained from the loss of function assays, TIGKs overexpressing A20 produced significantly less IL-6 and IL-8 following bacterial infection compared to the GFP expressing and A20 competent control cells." (PMID 32218782, 2020). "IFN-γ is mainly produced by NK cells and is one of the most important cytokines for the activation of granulocytes, which release proinflammatory cytokines such as IL-6 and IL-1β under bacterial infection." (PMID 33327533, 2020). "For the studied Th1 cytokines (IFNγ, TNFα, IL-6, and IL-1β), only IFNγ showed a significant decrease as a consequence of bacterial infection in mechanically ventilated rats." (PMID 31614857, 2019). "The immune response will be amplified by proinflammatory cytokine secretion, including TNF-α, IL-1, and IL-6, which help to enhance the tissue permeability and recruit more phagocytes to clear the bacterial infection." (PMID 30728747, 2019). "Several studies have suggested that pre-administration of CpG-DNA within three days before bacterial infection leads to the expression of several cytokines such as IL-6, IL-12, IFN-γ, and TNF-α, which enhances the host defense system." (PMID 31295956, 2019). "The heat map showed that the gene expression levels of 62 DEGs were upregulated and that some of these genes, such as IL-6, IL-1β, CCL2, CXCL2, CXCL8, and CSF3, are closely associated with host defense responses to bacterial infection." (PMID 31737164, 2019). "To date, three patients only were reported to suffer severe bacterial infections while having detectable neutralizing antibodies to IL-6 and impaired acute phase response." (PMID 31781117, 2019). "To determine if the IL-6 protein can dramatically increase resistance to secondary bacterial infections, we used exogenous recombinant mouse IL-6 protein to rescue bacterial resistance in IAV-infected mice." (PMID 32038632, 2019). "The production of IL-1β, IL-1α, TNF-α, and IL-6 was completely dependent on bacterial infection, but low levels of MCP-1 and MIP-1α were already detected in the supernatants from uninfected cultures." (PMID 30455194, 2019). "IL-6 is a proinflammatory cytokine, which, besides IL-8, is commonly used in pediatric clinical practice to monitor systemic inflammation and bacterial infection." (PMID 31824896, 2019). "Bacterial infection significantly induced the generation of IL-1β, IL-6, and TNF-α in BMMs treated with vehicle." (PMID 30609675, 2019). "These genes mediate the macrophage polarization to M1, a common response of macrophages to bacterial infections, which includes genes encoding TNF, IL-1β, IL-6, and CCL2." (PMID 30064361, 2018). "The product levels of IL-6, TNF-α, and NO in infected cells, which are representative biomaterials associated with bactericidal responses of macrophage to bacterial infection, were used as criteria for identifying differences in responses of infected cells." (PMID 30064361, 2018). "The cytokine IL-6 has proinflammatory activities and is required for the control of bacterial infection." (PMID 30169526, 2018). "The local response of IL-6 occurs at the bladder mucosal surface as a response to bacterial infections." (PMID 29796304, 2018). "In this stage of bacterial infection, pro-inflammatory cytokines such as TNF-α, IL-1β, and IL-6 are elevated, playing a crucial role in the pathogenesis of acute bacterial infection." (PMID 30319993, 2018). "PCT secretion is stimulated in bacterial infections by various cytokines, such as IL–1, IL–6, and tumor necrosis factor-alpha." (PMID 29891780, 2018).
bacterial infection (continued). "Amplification of leukocyte numbers during zebrafish bacterial infection has been shown to depend on signalling through the Csf3-Csf3r pathway, while both Csf3 and Interleukin-6 are known to be important in the response to yeast infection in mammalian systems." (PMID 29883484, 2018). "Inflammatory cytokine responses, including TNF, IL-1β, IL-6 and IL-12, mediate resistance to bacterial infection." (PMID 28580947, 2017). "Pro-inflammatory cytokines such as TNF-α, IL-6 and IL-1β are essential for the recruitment and activation of cells of the immune system in response to bacterial infection." (PMID 28440335, 2017). "Previous studies have shown that melatonin suppresses TNF-α, IL-1β, IL-6, IL-8, and IL-10 during bacterial infections or LPS treatment in vitro and in vivo." (PMID 28542575, 2017). "In contrast to the case during bacterial infection, similar TNFα and IL-6 levels were observed between the virus-infected WT and SCD animals." (PMID 28256526, 2017). "Among many miRNAs, the role of miR-155 is to upregulate proinflammatory cytokines, including TNF-α and IL6, in response to bacterial infection and chronic inflammation." (PMID 28507412, 2017). "Accordingly, blockade of trans-signaling was shown to be superior to total blockade of IL-6 signaling, for example, in mouse models for bacterial infection." (PMID 27493449, 2016). "Because TNF-α and IL-6 are both important cytokines contributing to the host immune system against bacterial infection, we examined these cytokines in the bladder tissues of the experimental mice using the ELISA method." (PMID 26233310, 2016). "Taken together, the present study provides evidence for the important role of TNFR1 and IL-6 as part of the innate immune response after bacterial infection." (PMID 27057100, 2016). "The majority of IL-6 (8/12; 67%) and IL-8 studies (5/6; 83.3%) reported statistically significant results to identify bacterial infections." (PMID 27486746, 2016). "In this study, we demonstrate that IFNα, a cytokine that modulates the early innate immune responses toward viral and bacterial infections, potently enhances the production of IL-6 in neutrophils stimulated with R848, a TLR8 agonist." (PMID 26790609, 2016). "IL-6 has been shown to be crucial for efficient neutrophil response against bacterial infections such as L. monocytogenes." (PMID 27548618, 2016). "In contrast, bacterial infections are commonly associated with an extensive release of IL-1β, thereby stimulating the hepatocytic CRP secretion through the induction of IL-6." (PMID 27977798, 2016). "For example, as the strongest activator of the hepatic acute-phase response, IL-6 mediates the secretion of a group of proteins, including C-reactive protein, serum amyloid A, haptoglobin, and α1-acid glycoprotein during bacterial infections." (PMID 27579592, 2016). "Many bacterial diseases are characterized by elevated levels of circulating IL-1β and IL-6 with a concomitant increase in plasma CRP, explaining the good correlation between plasma levels of IL-6 and CRP." (PMID 27977798, 2016). "IL-6 is a proinflammatory cytokine produced by macrophages, T lymphocytes, and fibroblasts in response to bacterial infection." (PMID 27403034, 2016). "We for the first time demonstrate that during bacterial infection, a Lyn–IL-6R–Ezrin complex negatively regulates the IL-6/STAT3 signaling pathway in murine AMs." (PMID 29263906, 2016). "For diagnosis of bacterial infection among preterm infants, the combination of IL-6 and CRP had a high sensitivity and specificity." (PMID 25894336, 2015). "By our study, we also demonstrated that EPs 7630 preincubation of immune cells influenced their subsequent, by viral or bacterial infection-mimicking agents induced cytokine production towards an IL-6-dominated milieu, with lower TNF-α and IL-10 content." (PMID 26406906, 2015).
bacterial infection (continued). "Upon screening for the expression of cytokines known to regulate intestinal defense mechanisms, IL-6 and IL-22 revealed strong induction after bacterial infection." (PMID 25799189, 2015). "Results presented in the present study, showing a strong correlation between IL-6 concentrations and Klebsiella pneumoniae, Pseudomonas aeruginosa and Enterococcus faecalis growth inhibition, support the role of IL-6 against bacterial infections." (PMID 26223356, 2015). "The APR is the first response to various stressors, such as injury, bacterial infection or systemic inflammation, and is activated by inflammatory mediators, such as tumor necrosis factor alpha (TNFα), IL-1β, IL-6, and GCs." (PMID 25335188, 2014). "Corresponding diagnostic AUCs for a proven bacterial infection were highest for presepsin and PCT (that is, presepsin, AUC = 0.908; PCT, AUC = 0.905) and lowest for IL-6 (that is, IL-6, AUC = 0.825)." (PMID 25190134, 2014). "The serum IL-1Ra levels of the patients with bacterial infections correlated positively with IL-6 (r = 0.635; P = 0.014), IL-8 (r = 0.671; P = 0.001), TNF-α (r = 0.701; P = 0.001), MCP-1 (r = 0.671; P = 0.001), and MIP-1β (r = 0.614; P = 0.04)." (PMID 23690657, 2013). "In response to bacterial infection, dendritic cells produce IL-6, TGF-β, and IL-1β that drive IL-17 production from innate lymphocytes." (PMID 23469071, 2013). "Upon exposure to bacterial infection, proinflammatory cytokines like TNFα, IL-1β, and IL-6 are secreted mostly by monocytes or macrophages to defend against bacterial infections." (PMID 23997804, 2013). "Lymphocytopenia, IL-10 and IL-6 concentrations on day 1 as well as noradrenalin and normetanephrin levels were highly correlated to the subsequent development of bacterial infections." (PMID 24069356, 2013). "It was recently shown that Interleukin-6 (IL-6) plays a beneficial role in anti-inflammatory activity to against bacterial infections, and enhances insulin action immediately at early recovery." (PMID 22553973, 2012). "In this study, at 24 h after bacterial infection, IL-6 immunoreactivity was present in supporting cells, olfactory ensheathing cells, fibroblasts, endothelial cells and innate immune cells." (PMID 22642871, 2012). "Conversely, a number of cells (e.g., macrophages and mast cells) and mediators (e.g., TNF-α and IL-6) improve host survival following severe bacterial infections." (PMID 22110673, 2011). "There is some modest supporting evidence from a trial of simvastatin in suspected or proven bacterial infection; reductions in tumor necrosis factor-α and interleukin-6 were demonstrated in the statin treated arm." (PMID 21541017, 2011). "During bacterial infection, inflammatory cytokines, such as IL-6, prompt the liver to increase the production of the iron metabolism regulatory peptide hepcidin, causing the internalization of ferroportin and thus preventing cellular iron export." (PMID 21501491, 2011). "It has been shown that IL-6 is produced following viral/bacterial infection and corneal transplantation." (PMID 18334954, 2008). "Previous studies have established the value of cytokines such as IL-6 and IL-8 to predict bacterial infection in the neonate with high sensitivity and specificity." (PMID 18321393, 2008). "IL-1, TNF-α, IL-6 are the early pro-inflammatory cytokines produced by monocytes after various bacterial infections and share a wide array of biological activities." (PMID 16504020, 2006). "For instance, monitoring PCT and IL-6 levels could help differentiate between bacterial and non-bacterial infections, influencing treatment decisions such as the need for antibiotics or immunomodulatory therapies." (PMID 41281283, 2025).
bacterial infection (continued). "Nevertheless, published studies suggest that PCT, as a bacterial infection marker, is widely used for both diagnosis and antibiotic stewardship, while IL-6 is a key inflammatory cytokine with high sensitivity but limited specificity due to its rise in diverse inflammatory conditions." (PMID 40568199, 2025). "A positive association with other proinflammatory acute-phase proteins, such as interleukin 1β (IL1β) and interleukin 6 (IL6), has been observed in viral and bacterial infections in humans, although the sensitivity and specificity of this relationship require further clarification." (PMID 40218414, 2025). "IL-6 significantly influences the immune response to bacterial infections." (PMID 40564288, 2025). "Although there was a significant reduction in IL‐10 levels in IL‐6‐deficient mice, this did not alter susceptibility to secondary bacterial infection." (PMID 39921246, 2025). "LPS, used as a positive control, elicited a typical cellular response to bacterial infection, triggering inflammatory and oxidative reactions including an increase in IL‐6 expression, a reduced expression of antioxidant genes, and an increase in ROS and mitochondrial superoxide levels." (PMID 40932751, 2025). "Significantly higher median levels of IL-6 were observed in the group of bacterial infections in the first days of the ICU stay, with the highest median levels on the day of ICU admission (3900.5 ng/L [IQR: 984.0–44,140.0] vs. 145.0 ng/L [IQR: 68.4–190.0]; p < 0.001)." (PMID 40733612, 2025). "However, the predictive value of CRP and IL-6 in differentiating bacterial infections among patients with DKA has yet to be investigated." (PMID 39946377, 2025). "Previous studies have shown that cirrhotic patients with bacterial infection exhibit excessive production of the inflammatory cytokines TNF-α and IL-6, which is associated with the development of an episode of extrahepatic organ failure and in-hospital mortality." (PMID 38413535, 2024). "In addition, IL‐6 is one of the detectable inflammatory cytokines in early serum and plays an important role in the process of bacterial infection, especially in the induction of CRP and fibrinogen synthesis in the liver." (PMID 38577990, 2024). "The down-regulated expression of so-called cell death related genes, including plk2 among others, and the up-regulated expression of inflammation related genes, including il6 among others, was shown in the hybrid grouper Epinephelus fuscoguttatus x Epinephelus lanceolatus after bacterial infection." (PMID 38983863, 2024). "Cytokine IL-6 plays a protective role in immune responses to bacterial infections." (PMID 39208074, 2024). "Besides, IL6 was related to bacterial infection and inflammation response, correlated IL6ST was reported to elevate when COPD aggravates." (PMID 39091676, 2024). "Additionally, while inflammatory cytokines like IL-6 are protective in immune responses to bacterial infections, they also promote osteoclast differentiation and inhibit osteoblast formation." (PMID 39208074, 2024). "Elevated levels of IL-6 have also been shown to assist in identifying bacterial infections." (PMID 39735250, 2024). "IL-6 is an important cytokine involved in the regulation of host response to bacterial infection." (PMID 38230738, 2024). "The laboratory test results of MPP group and RMPP group patients showed that the CRP, PCT, IL-6, and incidence of concurrent bacterial infections in MPP group patients were lower than those in RMPP group patients, and the difference was statistically significant." (PMID 39809213, 2024). "As a result, it has been suggested that IL‐6 cytokines may increase earlier than CRP during bacterial infections and enable early diagnosis." (PMID 38577990, 2024). "Moreover, IL-6 is an important cytokine involved in the regulation of the host response to bacterial infection." (PMID 39274511, 2024).
bacterial infection (continued). "Lipopolysaccharides (LPSs) from bacterial infections can enhance the inflammatory response by stimulating both IL-6 and IL-1β pathways, exacerbating cardiovascular inflammation and disease progression through increased cytokine production and systemic inflammation." (PMID 39057626, 2024). "In summary, we provide an extensive description of the monocyte-derived pro-inflammatory cytokine responses by preterm newborns and show that TLR-mediated production of TNF-α and IL-6 in the context of bacterial infections is comparable between preterm neonatal, term neonatal and adult WB." (PMID 38562936, 2024). "The results suggest that PMR may be an aberrant response to a bacterial infection with an exacerbated IL-6 and acute phase inflammatory response and molecular attempts to limit the inflammation." (PMID 38793033, 2024). "Our data showed that IL-6 was involved at the very beginning (D1) of the bacterial infection." (PMID 39208074, 2024). "In our longitudinal study, reductions in pro-inflammatory markers (CRP, IL6 and TNFα) and increments in anti-inflammatory markers (IL4) were associated with an improvement in CSDD and MMSE levels in patients recovering from a bacterial infection." (PMID 37762523, 2023). "Therefore, this study constructed a zebrafish (Danio rerio) il-6 knockout line by CRISPR/Cas9 to investigate the function of IL-6 in the liver post bacterial infection." (PMID 38139043, 2023). "Importantly, TNFA, IL1B, and IL6 were up-regulated in response to the bacterial infections in both epithelial A549 and monocyte U937 cells, as well as in vivo in the lungs." (PMID 37686095, 2023). "The cytokines TNF-α, IL-1α and IL-6 promote the synthesis of acute phase proteins such as C-reactive protein, by hepatocytes, the concentration of which is significantly increased during bacterial infection or tissue damage." (PMID 36937280, 2023). "But after bacterial infection with a fungus, the IL-6 has a strong sensitivity." (PMID 36319826, 2022). "Some scholars even found that IL-6/IL-10 could be used to identify G-/G+ bacterial infections in children." (PMID 35432366, 2022). "Therefore, we further studied the combination of IL-6 and IL-10 to identify G-/G+ bacterial infections." (PMID 35432366, 2022). "The AUC of IL-6 to predict bacterial infection was 0.679 (95% CI, 0.539–0.818)." (PMID 35391735, 2022). "Moreover, inflammatory factors such as TNF-α and IL-6 were dramatically decreased after Nano-MgB2 treatment, further demonstrating decreased bacterial infection and inflammation in Nano-MgB2-treated wounds." (PMID 36446788, 2022). "It has further been shown that the disease itself does not affect the susceptibility of IL-6 to bacterial infection in NHL patients." (PMID 35463642, 2022). "Patients with high IL-6 (≥ 390 pg/ml) were likely to be bacterial infection." (PMID 35391735, 2022). "For example, respiratory viruses trigger interferon production, which in turn upregulate interferon regulated genes to support apoptosis, while IL-6 and IL-8 are significantly upregulated in response to viral and bacterial infection to recruit neutrophils for clearance." (PMID 36618374, 2022). "However, during bacterial infections, the IL-6 concentration increases dramatically, and under severe conditions, it can even reach the μg/mL level, a range well within the detection limit to LFA systems." (PMID 35149284, 2022). "First, bacterial infection can augment the autoimmune response: Streptococcus combined with Veillonella isolated from the human small intestine microbiota inhibited IL-12p70 production and augmented IL-8, IL-6, IL-10 and TNF-α responses." (PMID 35847775, 2022). "In addition to culture-based diagnostic methods for the detection of bacterial infections, plasmatic infection biomarkers such as C-reactive protein (CRP), procalcitonin (PCT), and interleukin (IL)-6 have long been established in clinical practice." (PMID 35883545, 2022).